UROD (uroporphyrinogen decarboxylase)
Description:
Catalyzes the sequential decarboxylation of the four acetate side chains of uroporphyrinogen to form coproporphyrinogen and participates in the fifth step in the heme biosynthetic pathway. Isomer I or isomer III of uroporphyrinogen may serve as substrate, but only coproporphyrinogen III can ultimately be converted to heme. In vitro also decarboxylates pentacarboxylate porphyrinogen I.
Synonyms: UPD; PCT
Tractability: Small molecule: a structure with a bound ligand is known; it has a high-quality binding pocket. PROTAC: ubiquitination databases record sites on it; its protein half-life has been measured.
Target class: Enzyme; Lyase
Safety:
Unwanted effects reported when the protein is acted on. In parentheses: how it was acted on, where the effect was seen, and who reports it.
Uroporphyria (inhibition; source: AOP-Wiki)
Gene: Protein-coding gene on chromosome 1 (45,010,950 to 45,015,575, forward strand). Ensembl gene ENSG00000126088.
Subcellular location: Cytoplasm, cytosol
Subcellular location (Human Protein Atlas): Cytosol; Nucleoplasm
Pathways (Reactome):
Metabolism: Heme biosynthesis
Gene Ontology:
Molecular function: protein binding; uroporphyrinogen decarboxylase activity
Biological process: heme B biosynthetic process; porphyrin-containing compound catabolic process; porphyrin-containing compound metabolic process; heme biosynthetic process; heme A biosynthetic process; porphyrin-containing compound biosynthetic process
Cellular component: cytosol; nucleoplasm
Genetic constraint (gnomAD): Loss-of-function variants: 34 observed, 49.53 expected, observed/expected ratio (o/e) 0.69, 90% interval 0.52 to 0.91. The upper end of that interval is the gene's LOEUF score, 0.91, which puts it in group 3 of 6, group 1 being the genes least tolerant of losing a copy. Missense variants: 381 observed, 499.45 expected, observed/expected ratio (o/e) 0.76, 90% interval 0.7 to 0.83. Synonymous variants: 148 observed, 186.13 expected, observed/expected ratio (o/e) 0.8, 90% interval 0.69 to 0.91.
Gene-disease validity (ClinGen):
ClinGen rates the evidence that UROD causes each of these diseases.
UROD-related inherited porphyria (semidominant): Definitive. Porphyria caused by monoallelic and biallelic variants in UROD and presenting as a spectrum of disease (a semidominant inheritance pattern).
Homologues: Orthologues: chimpanzee UROD (99% identical), macaque UROD (99% identical), rabbit UROD (95% identical), pig UROD (95% identical), rat Urod (93% identical), guinea pig UROD (93% identical), mouse Urod (93% identical), dog UROD (79% identical), tropical clawed frog urod (71% identical), zebrafish urod (68% identical), Drosophila melanogaster Urod (52% identical). Paralogues in human: MTR (21% identical), MTHFR (17% identical), BHMT (15% identical), BHMT2 (14% identical).
Diseases named in the same sentence as UROD in open-access papers:
UROD is named in the same sentence as 37 diseases in open-access papers, as found by Europe PMC text mining. Sharing a sentence is not in itself a finding about the gene and the disease. The quoted sentences say what the papers report.
porphyria (18 papers, 2008 to 2025). Porphyria is a group of diseases in which substances called porphyrins build up, negatively affecting the skin or nervous system. "Porphyria cutanea tarda (PCT) is the most common subtype of porphyria and results from a deficiency of the enzyme uroporphyrinogen decarboxylase." (PMID 40167326, 2025). "Porphyria cutanea tarda (PCT), the most common form of porphyria, is caused by a deficiency of the fifth enzyme of the heme biosynthesis pathway, uroporphyrinogen decarboxylase (UROD)." (PMID 37216149, 2023). "Porphyria cutanea tarda (PCT) is the most common porphyria and is due to deficient activity of uroporphyrinogen decarboxylase (UROD)." (PMID 33123388, 2020). "Porphyria cutanea tarda (PCT) is the most common of the cutaneous porphyrias and is caused by a deficient level of uroporphyrinogen decarboxylase (UROD)." (PMID 29553924, 2018). "Porphyria cutanea tarda (PCT), the most common of the human porphyrias, arises from a deficiency of uroporphyrinogen decarboxylase." (PMID 29856826, 2018). "PCT, the most common type of porphyria, is associated with a defect in uroporphyrinogen decarboxylase (UROD), the fifth enzyme in the heme biosynthetic pathway in the liver." (PMID 29856826, 2018). "Porphyria cutanea tarda, caused by deficiency of hepatic uroporphyrinogen decarboxylase, is the most common porphyria." (PMID 26660706, 2016). "Levels and patterns of porphyrins were within the normal ranges, confirming that HCB concentrations at current levels are unable to inhibit uroporphyrinogen decarboxylase and cause clinical or subclinical porphyria." (PMID 18941586, 2008). "PCT, the most common type of porphyria, is in most cases (type I) an acquired deficiency of Uroporphyrinogen decarboxylase (UROD), the fifth enzyme in heme biosynthesis, caused by underlying liver diseases triggered by alcohol, iron overload, chlorinated hydrocarbons, oestrogens or viral hepatitis." (PMID 39135705, 2024). "This case highlights the limitations of rigid UROD‐related porphyria classifications and supports the existence of a phenotypic continuum modulated by genetic, epigenetic, and environmental factors." (PMID 40534320, 2025). "Porphyria cutanea tarda (PCT) is a hepatic and metabolic disorder caused by a defect of the hepatic enzyme uroporphyrinogen decarboxylase (UROD)." (PMID 35193623, 2022). "Porphyria cutanea tarda (PCT) results from a defect of hepatic enzyme uroporphyrinogen decarboxylase (UROD)." (PMID 30944007, 2019). "Porphyria cutanea tarda (PCT), the most common subtype of porphyria, is characterized by the deficient activity of uroporphyrinogen decarboxylase (UROD), leading to the accumulation of porphyrins resulting in photosensitive blistering skin lesions and liver dysfunction." (PMID 39568488, 2024). "Uroporphyrins are produced in porphyrias with decreased activity of PBGD, UROS, and UROD." (PMID 29238562, 2017).
porphyria cutanea tarda (18 papers, 2014 to 2026). The most common form of chronic hepatic porphyria. "Heterozygous pathogenic UROD variants are typically associated with porphyria cutanea tarda (PCT), while homozygous or compound heterozygous variants cause hepatoerythropoietic porphyria (HEP), a rarer and more severe phenotype." (PMID 40534320, 2025). "We report a patient homozygous for the UROD c.185C>T (p.P62L) variant who presents with clinical features resembling familial porphyria cutanea tarda (PCT)." (PMID 40534320, 2025). "Porphyria cutanea tarda (PCT) is a skin disorder caused by a defect in the liver enzyme uroporphyrinogen decarboxylase and is associated with hepatitis C virus infection, high alcohol intake, smoking and iron overload." (PMID 35193623, 2022). "UROD participates in the biosynthesis of heme in mammals, and mutations in UROD cause familial porphyria cutanea tarda, which results in skin fragility and blisters." (PMID 34445083, 2021). "Humans deficient in UROD present with porphyria cutanea tarda (PCT), a condition characterized by light-sensitive dermatitis, excretion of excess uroporphyrins, and associated hepatic porphyrin accumulation." (PMID 24587102, 2014). "Some patients with porphyria cutanea tarda, caused by mutations in the uroporphyrinogen decarboxylase gene, exhibit similar photosensitivity, and fragility, leading to repeated blistering and fissuring that progresses to fibrosis and becoming sclerodermatous in the late stages." (PMID 36967721, 2023). "Porphyria cutanea tarda (PCT), caused by hepatic uroporphyrinogen decarboxylase deficiency, may rarely overlap with undiagnosed celiac disease (CD), complicating diagnosis due to shared hepatic and dermatologic features." (PMID 41675771, 2026). "A UROD+/− murine model of porphyria cutanea tarda (PCT), a genetic disease caused by UROD loss of activity, induced a 2-fold UROD activity decrease, which did not result in hepatic porphyrins accumulation, indicating the enzyme is not rate limiting." (PMID 35887311, 2022). "Porphyria cutanea tarda (PCT) is the most common type of porphyria worldwide, with an incidence between 20,000–70,000, and it encompasses a group of disorders caused by an insufficient/altered UROD enzymatic activity." (PMID 35204362, 2022). "Porphyria cutanea tarda (PCT) is a skin disorder originating from a deficit of the liver enzyme uroporphyrinogen decarboxylase." (PMID 30944007, 2019).
head and neck cancer (4 papers, 2012 to 2022). A primary or metastatic malignant neoplasm affecting the head and neck. "Porphyrin accumulation-based radiodynamic therapy showed encouraging results in a head and neck cancer model with the invalidation of Uroporphyrinogen III decarboxylase UROD, the fifth enzyme of the pathway." (PMID 36077783, 2022). "Uroporphyrinogen decarboxylase (UROD) has been suggested as a protectant against radiation for head and neck cancer (HNC)." (PMID 23209648, 2012). "Indeed, uroporphyrinogen decarboxylase (UROD) downregulation altered iron homeostasis in a head and neck cancer model, produced reactive oxygen species, and enhanced radiotherapy." (PMID 36077783, 2022).
cutaneous porphyria (3 papers, 2023 to 2024). An erythropoietic porphyria (massive accumulation of photoreactive porphyrins in the bone marrow erythroid cells and circulating erythrocytes, resulting in cutaneous photosensitivity) caused by biallelic variants in UROS (in an autosomal recessive inheritance pattern). "PCT, the most prevalent form of cutaneous porphyria, is caused by the inhibition of uroporphyrinogen decarboxylase (UROD)." (PMID 38352109, 2024).
hepatoerythropoietic porphyria (3 papers, 2014 to 2025). A very rare form of chronic hepatic porphyria characterized by bullous photodermatitis. "UROD mutation homozygosity or compound heterozygosity causes the rare hepatoerythropoietic porphyria (HEP), which presents with pink/red-colored urine, bullous skin lesions on light-exposed areas of the skin, hypertrichosis, skin fragility, and disfiguring skin thickening/scarring." (PMID 24587102, 2014).
iron overload (3 papers, 2022 to 2025). "Despite the absence of UROD gene mutations, the interplay between pSS, iron overload, and medication exposure supported a diagnosis of sporadic PCT." (PMID 40821324, 2025).
glioma (2 papers, 2020 to 2021). A benign or malignant brain and spinal cord tumor that arises from glial cells (astrocytes, oligodendrocytes, ependymal cells). "In this sense, we recently observed significant differences in the mRNA expression in 8 of 11 analyzed genes (HMBS, UROD, FECH, PPOX, SLC15A2, ALAD, UROS, and ABCB6) involved in the heme biosynthesis between WHO grade II and IV gliomas." (PMID 33562253, 2021). "Significant differences in mRNA expression included increases of HMBS, UROD, FECH and PPOX as well as decreases of SLC15A2, ALAD, UROS and ABCB6 in WHO IV gliomas." (PMID 32722247, 2020). "Interestingly, however, in only three genes mRNA expression (HMBS, UROD and PPOX) was altered in the direction expected to result in increased PpIX concentrations in WHO grade IV gliomas, whereas the remaining 5 up-/downregulations were actually observed in the respective opposite directions." (PMID 32722247, 2020).
cervical carcinoma (1 paper, 2014). A carcinoma arising from either the exocervical squamous epithelium or the endocervical glandular epithelium. "UROD inhibition using siUROD was previously characterized in FaDu (human hypopharyngeal squamous carcinoma), ME-180 (human cervical carcinoma), and NOE (human normal oral epithelial) cells; we therefore evaluated PI-16 on the same cell lines." (PMID 24587102, 2014).
glaucoma (1 paper, 2021). Increased pressure in the eyeball due to obstruction of the outflow of aqueous humor. "The AL590666.2-hsa−miR−339−5p-UROD axis was recognized to be able to stably distinguish between POAG and non-glaucoma individuals." (PMID 34926471, 2021).
hemochromatosis (1 paper, 2021). A disorder of iron metabolism characterized by a triad of HEMOSIDEROSIS; LIVER CIRRHOSIS; and DIABETES MELLITUS. "UROD is inactivated in an iron-dependent process, explaining the mechanistic link between hemochromatosis and PCT." (PMID 34367815, 2021).
hepatic porphyria (1 paper, 2014). A group of metabolic diseases due to deficiency of one of a number of liver enzymes in the biosynthetic pathway of heme. "Mutations in the Urod gene cause a cutaneous form of hepatic porphyria, called porphyria cutaneous tarda (PCT; OMIM: #176100); impaired UROD activity leads to the accumulation of uroporphyrin and other highly carboxylated porphyrins in the skin, liver and erythrocytes." (PMID 24782769, 2014).
hypersomnia (1 paper, 2023). A sleep disorder characterized by excessive sleepiness. "Six (GPX4, PSMB5, PSMB6, PRDX5, ASNA1, EIF4H) out of seven hub genes were associated with the expression of insomnia/hypersomnia only in females, while UROD was the only hub gene common to both sexes." (PMID 37884562, 2023).
lung adenocarcinoma (1 paper, 2021). A carcinoma that arises from the lung and is characterized by the presence of malignant glandular epithelial cells. "Another closely similar CRISPR genome screening approach was employed to identify regulators of PD‐L1 expression in H358 lung adenocarcinoma; the authors identified SMAD4 and uroporphyrinogen decarboxylase (UROD) in addition to CMTM6 as novel regulators of PD‐L1 expression." (PMID 34188916, 2021).
melanoma (1 paper, 2022). A malignant, usually aggressive tumor composed of atypical, neoplastic melanocytes. "We performed the same IFNγ-R1 regulator screen in a second human melanoma cell line, SK-MEL-23, which was similar in quality and again identified STUB1 and UROD." (PMID 35395848, 2022).
cancer (11 papers, 2013 to 2024). A tumor composed of atypical neoplastic, often pleomorphic cells that invade other tissues. "The enzyme encoded by UROD is involved in this pathway and was recently identified as a potential anti-cancer target due to its ability to convert uroporphyrinogen to coproporphyrinogen." (PMID 33424926, 2020). "Notably, the highest cancer gene essentiality was attributed to the genes encoding enzymes responsible for the fifth and sixth steps of the pathway, namely uroporphyrinogen III decarboxylase (UROD) and coproporphyrinogen III oxidae (CPOX), respectively." (PMID 39062740, 2024). "ENO3, OSTC, and UROD serve as diagnostic or prognostic biomarkers in other cancers." (PMID 36826154, 2023). "This 1st generation UROD inhibitor reduced cancer cell viability, while having limited effects on normal cells." (PMID 24587102, 2014). "Sudden perturbation of iron homeostasis by UROD inhibition in cancer cells is thought to be at least partially responsible for the effectiveness of UROD as an anticancer target." (PMID 24587102, 2014). "In addition, patients with higher UROD expression were more likely to have shorter disease-free survival, suggesting the involvement of UROD in cancer progression." (PMID 26516850, 2015). "On this basis, we propose that the design and preparation of additional UROD inhibitors could have a role to play in the generation of yet-improved cancer therapies and radiation sensitizers." (PMID 24587102, 2014). "The discovery and characterization of UROD inhibitors is an important translational opportunity in cancer because such chemicals may provide a potential strategy for single-agent efficacy, radiosensitization, and/or chemosensitization in a broad range of human malignancies." (PMID 24587102, 2014). "It is therefore anticipated that UROD inhibition may be tolerated for cancer therapy." (PMID 24587102, 2014). "Incidentally, overexpression of the human orthologue UROD has been associated with diseases involving porphyrin metabolism and cancer and enhancement in the activity and concentration of TKLT1 are highly correlated with rate of tumour growth in a variety of cancers." (PMID 23970950, 2013). "Significantly, these cancer cell lines developed dependencies on heme metabolism–related proteins, such as uroporphyrinogen III decarboxylase (UROD), the enzyme that catalyzes the fifth step in the heme biosynthetic pathway." (PMID 38649187, 2024). "The present system and future UROD inhibitors will facilitate investigations into the use of UROD inhibition as a means of achieving control across a wide variety of cancers, with and without combination therapy." (PMID 24587102, 2014). "In addition, cancer/AML progenitor cells exhibited imbalanced heme biosynthesis, inferred and exemplified by elevated gene expression for enzymes that catalyze the intermediate steps of heme biosynthesis, for example, HMBS and UROD." (PMID 38649187, 2024).
tumor (7 papers, 2012 to 2025). "Uroporphyrinogen decarboxylase (UROD) has been implicated as a tumor-selective protectant for HNC against radiation." (PMID 23209648, 2012). "The limited capacity of ferrochelatase (FECH) and increased enzymatic activity of ALA dehydratase (ALAD), porphobilinogen deaminase (PBGD) and uroporphyrinogen decarboxylase (UROD) result in the accumulation of exogenous PpIX in tumor cells." (PMID 33171665, 2020). "There is evidence showing the involvement of increased UROD gene expression or enzyme activity in tumor initiation and progression." (PMID 26516850, 2015). "Overexpression of UroD has been recently demonstrated in tumour biopsies of patients with head and neck cancer." (PMID 23970950, 2013). "UROD expression was significantly elevated in tumor biopsies from head and neck cancer patients." (PMID 26516850, 2015). "Additionally, enhanced activity of enzymes leading to the production of PpIX, such as aminolevulinate dehydratase (ALAD), uroporphyrinogen decarboxylase (UROD), and hydroxymethylbilane synthase (HMBS), has been observed in tumor cells." (PMID 35456936, 2022).
UROD also shares sentences with these, for which no sentence is quoted: metabolic disorder (3 papers); hepatitis C (2); liver disease (2); sarcoma (2); skin disorder (2); viral hepatitis (2); anemia (1); celiac disease (1); chronic myeloid leukemia (1); genetic disease (1); head and neck squamous cell carcinoma (1); infection (1); infectious disease (1); insomnia (1); liver dysfunction (1); maturity-onset diabetes (1); mental retardation (1); neurological disorders (1); Sepsis (1); superficial epidermolytic ichthyosis (1); viral infections (1).